RNF6 (ring finger protein 6)
Diseases named in the same sentence as RNF6 in open-access papers (continued):
Sharing a sentence is not in itself a finding about the gene and the disease.
tumor (continued). "Moreover, the IB analyses on tumor tissues from xenografts showed that overexpression of TRIM26 decreased PBX1 and RNF6, while knockout of TRIM26 led to upregulation of PBX1 and RNF6." (PMID 37324936, 2023). "In line with our previous data, RNF6 overexpression accelerated tumor growth in the group without pladienolide B treatment." (PMID 34611311, 2021). "To evaluate whether RNF6 induces tumor progression through regulating SF3B2, we transfected SF3B2 knockout HCT116 and HT29 cells with RNF6 expression plasmid or empty vector." (PMID 34611311, 2021). "Moreover, RNF6 plays a critical factor in AML cell proliferation, tumor progression, and chemoresistance." (PMID 29997504, 2018). "In AML cells, RNF6 promotes AML cell proliferation and tumor growth." (PMID 29997504, 2018).
hematological malignancies (2 papers, 2017 to 2022). "It will be of interest to know whether induction of RNF6 auto-ubiquitination benefits the treatment of hematological malignancies." (PMID 35926709, 2022).
infection (1 paper, 2022). The state of being infected such as from the introduction of a foreign agent such as serum, vaccine, antigenic substance or organism. "Upon infection, the direct interaction of RNF6, a RING-type E3 ligase, mediated QKI ubiquitination degradation and facilitated PI3K-p110β related autophagic removal of pathogen." (PMID 36088389, 2022). "Taken together, the up-regulated Rnf6 post-infection promoted QKI degradation and facilitated the release of PI3K-p110β mRNA from P body to activate translation, ending up with its higher expression and the enhanced autophagy." (PMID 36088389, 2022). "RNF6 level was significantly increased in macrophages post-infection." (PMID 36088389, 2022). "The co-immunoprecipitation analysis showed that Rnf6 could interact with QKI in macrophages regardless of infection." (PMID 36088389, 2022).
RNF6 also shares sentences with these, for which no sentence is quoted: acute myeloid leukemia (2 papers); myeloma (2); acute leukemia (1); adenocarcinoma (1); Cachexia (1); chronic leukemia (1); diabetes (1); ductal carcinoma (1); glioblastoma (1); invasive ductal breast carcinoma (1); lung adenocarcinoma (1); multiple myeloma (1); non-small cell lung carcinoma (1); retinoblastoma (1); squamous cell carcinoma (1); type 2 diabetes (1).